MBD2 (methyl-CpG binding domain protein 2)
Diseases named in the same sentence as MBD2 in open-access papers (continued):
Sharing a sentence is not in itself a finding about the gene and the disease.
cancer (43 papers, 2001 to 2026). A tumor composed of atypical neoplastic, often pleomorphic cells that invade other tissues. "We believe that this phenotype caused by the enhancing effect of MBD2 siRNA on inducing cancer cell apoptosis." (PMID 37142578, 2023). "Many studies have attempted to link loss of MBD2 or MBD3 to significantly increased cancer predisposition in human patients, but evidence for this is limited." (PMID 27303433, 2016). "Since promoter hyper-methylation is a well-known hallmark of cancer, several studies linked MBD2 function to epigenetic regulation of genes critical during carcinogenesis, however, most of these studies looked at a limited number of target genes." (PMID 24927503, 2014). "This occurs through the downregulation of DNA methyltransferases DNMT1, DNMT3A, and DNMT3B, and the upregulation of Methyl CpG Binding Domain Protein 2 (MBD2), a marker often associated with cancer due to its role in causing genomic instability and increasing mutation frequencies." (PMID 39829957, 2025). "Moreover, MBD2 encoded protein is associated with many types of cancer, such as breast, renal, colorectal and prostate." (PMID 37359372, 2023). "We previously identified that ROS‐dependent expression of epigenetic reader methyl‐CpG‐binding domain protein 2 (MBD2), specifically the alternative mRNA splicing variant MBD2_v2, is crucial for maintenance and expansion of self‐renewing cancer stem cell‐like cells (CSCs) in TNBC cell cultures." (PMID 30636104, 2019). "Using a panel of PCa cells, including cell lines from AAM, we also elucidated that exogenous IL‐6 upregulated expression of the epigenetic reader methyl CpG binding domain protein 2 (MBD2), specifically the alternative mRNA splicing variant MBD2_v2, to promote cancer stem‐like cells (CSCs)." (PMID 29741809, 2018). "Loss of MBD2 has complex effects on gene expression with both upregulation and downregulation of many genes, which differentially affects tumorigenesis in various mouse cancer cell lines and in human cancer cell xenografts in mice." (PMID 27303433, 2016). "In conclusion, δEF1 may associate with DNMT1, as well as MBD2 and 3, to establish and/or maintain methylation patterns in the E-cadherin promoter region in cancer cells." (PMID 25315069, 2015). "Given that there is a potential role for MBD2 in tumorigenesis, we hypothesized that genetic polymorphisms in the MBD2 gene may modify an individual's susceptibility to human cancers." (PMID 16168120, 2005). "In our study, we found MBD2 upregulation in cancers including HNSCC, correlating with poor clinicopathological features." (PMID 39676597, 2024). "Future animal studies in vivo are required to establish the plausibility of knockdown MBD2 or overexpression p21 in naked mice that is proposed here to retard cancer progression." (PMID 39676597, 2024). "In an experiment with mice, it was found that removing MBD2 slowed down the formation of tumors and reduced the spread of cancer." (PMID 38556549, 2024). "Since we also found impairment of PI3K-AKT activation, which is required for cancer growth and invasion, we propose that Mbd2 likely regulates the PI3K-AKT pathway through transcriptional regulation of the genes encoding Sparc and OPN." (PMID 38556549, 2024). "MBD2 was found to control several genes involved in how cancer progresses and how the immune system responds." (PMID 38556549, 2024). "Given that MBD2 itself does not influence DNA methylation and seems to be dispensable for the biological processes under physiological conditions, MBD2 is likely to be a viable target to suppress cancer metastasis." (PMID 37142578, 2023). "The Methyl-CpG-binding domain 2 (Mbd2) binds methylated DNA and was shown to play an important role in cancer and immunity." (PMID 37443311, 2023). "More recently, studies indicate that MBD2 probably modulates tumorigenesis in different types of cancer." (PMID 37142578, 2023).
cancer (continued). "In summary, this study indicated that MBD2 facilitates cancer metastasis, and therefore, knockdown of MBD2 inhibited TGF-β1-induced EMT, migration and invasion of cancer cells." (PMID 37142578, 2023). "We thus stimulated A549, H1975 and B16F10 cells with TGF-β1 to assess the impact of MBD2 on cancer cell EMT process." (PMID 37142578, 2023). "Adopting the findingsof this study into hmDNA enrichment of clinical samples has the potentialto become more selective and sensitive than current MBD2-based methodsand, therefore, to improve cancer diagnostics." (PMID 36052432, 2022). "MBD2 belongs to the family of the methyl-CpG-binding domain proteins and has been connected to multiple diseases, such as cancers and inflammations." (PMID 35785161, 2022). "Our group has previously shown that the treatment of cancer cells with the universal methyl group donor S-adenosylmethionine (SAM) downregulates MBD2 expression and shows anti-proliferative and anti-metastatic effects both in vitro and in vivo." (PMID 31245293, 2019). "Molecular action of selected leads inhibiting the targeted PPI of MBD2 was validated in vitro and in cell, followed by confirming their inhibitory effects on the epithelial-mesenchymal transition of various cancer cells." (PMID 31799386, 2019). "Using this novel approach, we identified two small-molecule compounds capable of inhibiting the PPI of MBD2 and thereby efficiently suppressing the cancer metastatic potentials." (PMID 31799386, 2019). "In particular, the cell migration assay was used for this preliminary test of the compounds on the basis of the previous observation that knockdown of MBD2 in cancer cell lines resulted in decreased migration of the cells." (PMID 31799386, 2019). "The expression of MBD2 gene was downregulated when the cancer cells were treated with the naturally occurring methyl group donor SAM that shows anti-proliferative and anti-metastatic effects." (PMID 31245293, 2019). "CFP1 is closely related to MBD1, MBD2 on the 18q21 chromosome, a region that is often damaged in cancer." (PMID 31496919, 2019). "MBD2 has been shown to directly repress human telomerase reverse transcriptase (hTERT) in several cancer cell types." (PMID 27303433, 2016). "Studies of MBD2 in human cancer patients also point to MBD2 as a potential regulator of tumorigenesis." (PMID 27303433, 2016). "Inhibition of mbd2 by antisense expression results in inhibition of anchorage-independent growth of antisense transfected cancer cells or cells infected with an adenoviral vector expressing antisense mbd2." (PMID 24255851, 2013). "Although targets of MBD2 have been identified to play functional roles in cancer, few have identified targets that exert direct higher-order regulation such as a microRNAs or transcription factors." (PMID 24204564, 2013). "Although our understanding of the exact function of MBD2 in epigenetics is still in its early stages, several studies in human cancer research have demonstrated that the MBD2 protein plays a role in tumorigenesis." (PMID 16168120, 2005). "In the past few years, our laboratory has concentrated on the effect of MBD2 on cancer progression." (PMID 37142578, 2023). "MBD2 participates in gene silencing and has active role in shaping the cancer methylome." (PMID 32583859, 2020). "Moreover, antisense oligonucleotides against MBD2 gene also showed promising anti-cancer effects in xenograft models." (PMID 31245293, 2019). "The intrinsically disordered region of MBD2 is a promising target for treating cancer metastasis." (PMID 31799386, 2019). "Based on these preclinical data, the genes transcriptionally regulated by Mbd2 within the immune system and stem cells from the normal and diseased intestinal epithelia offer a set of targets that play a key role in linking epigenetic changes to cancer." (PMID 29603746, 2018).
cancer (continued). "Future investigations into MBD2 functions may have important implications for the study of pluripotency, immunity, and cancer, in addition to revealing insights into broader epigenetic mechanisms." (PMID 27303433, 2016). "The functions of MBD2 may have direct therapeutic implications for several areas of human disease, including autoimmune conditions and cancer, in addition to providing insights into the actions of NuRD and chromatin regulation." (PMID 27303433, 2016). "Despite the absence of mutations in MBD2 or MBD3 in cancer, there is evidence that these genes show altered regulation in tumors." (PMID 27303433, 2016). "Future studies need to test the hypothesis that this is a mechanism for a coordinated repression of important gene networks in cancer by DNA methylation regulators such as MBD2." (PMID 24204564, 2013). "Its silencing by overexpression of MBD2 through hsa-mir-496 is consistent with a role in cancer." (PMID 24204564, 2013). "The results described here offer a different mechanism by which MBD2 could affect gene expression in cancer and other physiological states: coordinated repression of genes through activation of microRNA." (PMID 24204564, 2013). "Thus, Mbd2 serves as an activator of several cancer genes in our model." (PMID 38556549, 2024). "Furthermore, it is also stated that MBD2 can correlate with cancer angiogenesis." (PMID 35785161, 2022). "These mutations represent additional insight into how genes such as IGF1R, MSI2, MBD2, and ASCL1 can be aberrantly regulated in cancer, highlighting the importance of expanding the field’s view of cancer genomics to include alterations in UTRs." (PMID 37516102, 2023). "Therefore, MBD2 may be a common suppressor for several cancer types, which is similar to circKCNN2." (PMID 35051313, 2022). "Emerging evidence shows that methyl-CpG-binding domain protein 2 (MBD2), a DNA methylation reader, often participates in the transcriptional silencing of hypermethylated genes in cancer cells." (PMID 34789717, 2021). "To explore the potential clinical relevance of MBD2 expression in AML patients and in the normal population, we searched the GEPIA website and found that MBD2 was overexpressed in several types of cancer, such as AML." (PMID 34789717, 2021). "Concerning this study, we have recently identified the MBD2-p66α molecular system in Mi-2/NuRD CRC as a promising target for EMT modulation by observing the induction of MET (conversed process of EMT) by knockdown of MBD2 and/or p66α in cancer cells." (PMID 31799386, 2019). "Even though MBD2 is an attractive anti-cancer target, drugs that can specifically target MBD2 have not been identified to date." (PMID 31245293, 2019). "Therefore, the focus of studies on MBD2 and MBD3 in cancer has shifted to their potential as therapeutic targets." (PMID 27303433, 2016). "Interestingly, the Mbd2−/− mice did not develop autoimmunity which makes it an attractive target in pathological conditions like cancer where the Tregs have been suggested as potential targets for immunotherapy." (PMID 31245293, 2019).
infection (7 papers, 2011 to 2024). The state of being infected such as from the introduction of a foreign agent such as serum, vaccine, antigenic substance or organism. "Taken together, these results indicate that Vancomycin-Loaded Calcium Sulfate promotes M2 cell polarization through upregulation of MBD2 expression, thereby preventing open fracture infection in a mouse model." (PMID 39198853, 2024). "In summary, our study discovered that Vancomycin-Loaded Calcium Sulfate can prevent open fracture infection by regulating MBD2-mediated macrophage polarization." (PMID 39198853, 2024). "However, the exact mechanism of utilizing MBD2 to mediate macrophage polarization and combat open fracture infections remains unresolved." (PMID 39198853, 2024). "Significant differences were also noted in MBD2 levels with HPV infection and HPV/p16 infection." (PMID 39676597, 2024). "mBD2 expression is induced during infection with Gram-negative bacteria, their products (e.g. lipopolysaccharide), and various proinflammatory cytokines (e.g. tumour necrosis factor)." (PMID 27655266, 2016). "We performed real time qRTPCR for mBD2, mBD3 and Cnlp (CRAMP) before and 48 hours after infection." (PMID 26332373, 2015). "This study primarily discovered that the Vancomycin-Loaded Calcium Sulfate combined with a negative pressure drainage device may prevent open fracture infection by modulating the macrophage polarization through the methyl-CpG binding protein MBD2." (PMID 39198853, 2024). "In correlation with these in vitro data, we found mRNA expression of mBD2 and mouse cathelicidin-related antimicrobial peptide (mCRAMP) was significantly augmented in AKB-4924 treated mice compared to vehicle-treated mice 18 h post-infection by approximately 4-fold." (PMID 25927232, 2015).
bacterial infection (2 papers, 2023 to 2026). "Collectively, these findings suggest that MBD2 epigenetically represses HLA-DR expression in monocytes, leading to impaired antigen presentation and immune paralysis, thereby predisposing patients with HBV-ACLF to secondary bacterial infections." (PMID 41789066, 2026). "Among the notable observations from applying GRaNIE and GRaNPA to study the gene expression response in macrophages was that some TFs, including MBD2, were specifically important only for predicting response to bacterial infection, and not for IFN‐γ stimulation." (PMID 37073532, 2023).
inflammation (2 papers, 2021 to 2022). Aberrant reaction of the microcirculation characterized by movement of fluid and leukocytes from the blood into extravascular tissues. "However, Mbd2-CKO mice displayed remarkably lower inflammatory scores, suggesting that loss of Mbd2 in macrophages markedly alleviated OVA-induced airway inflammation." (PMID 36090987, 2022).
intestinal disease (1 paper, 2018). "At 180 days following exposure to 2% DSS in drinking water given ad libitum, these mice, in contrast to the systemic Mbd2−/− setting, showed no signs of intestinal disease (data not shown)." (PMID 29603746, 2018). "The control Mbd2+/+ littermates made a complete recovery following withdrawal of DSS and at 30 (N = 9) and 170 days (N = 11) post‐inflammation showed no sign of intestinal disease." (PMID 29603746, 2018).
kidney disease (1 paper, 2019). "Patients with severe kidney disease exhibited a slight increase in DNMT1 transcription, accompanied with small downregulation of MBD2." (PMID 31507612, 2019).
neurological disorders (1 paper, 2025). "MBD2 has been found to be associated with neurodevelopmental and neurological disorders." (PMID 39800672, 2025).
MBD2 also shares sentences with these, for which no sentence is quoted: adenocarcinoma (4 papers); cholangiocarcinoma (2); epilepsy (2); glioblastoma (2); acute lymphoblastic leukemia (1); acute-on-chronic liver failure (1); airway hyperresponsiveness (1); Allergy (1); Calcium nephrolithiasis (1); cervical squamous cell carcinoma (1); chronic kidney disease (1); chronic myeloid leukemia (1); corneal infection (1); endocervical adenocarcinoma (1); Hyperglycemia (1); interstitial lung disease (1); intestinal inflammation (1); invasive breast ductal carcinoma (1); large cell carcinoma (1); liver cancer (1); liver disease (1); medulloblastoma (1); mental retardation (1); myelodysplastic syndrome (1); nephritis (1); non-small cell lung carcinoma (1); papillary thyroid cancer (1); pulmonary hypertension (1); renal failure (1); Rett syndrome (1).
A further 8 diseases each share a sentence with MBD2 in 1 paper.